RN7SL218P (RNA, 7SL, cytoplasmic 218, pseudogene)
Gene: Miscellaneous RNA gene on chromosome 4 (74,011,578 to 74,011,876, forward strand). Ensembl gene ENSG00000244194.
Homologues: Orthologues: chimpanzee Metazoa_SRP (99% identical), macaque Metazoa_SRP (91% identical). Paralogues in human: RN7SL1 (85% identical), RN7SL2 (84% identical), RN7SL3 (84% identical), RN7SL559P (82% identical), RN7SL301P (82% identical), RN7SL44P (81% identical), RN7SL187P (81% identical), RN7SL322P (81% identical), RN7SL122P (81% identical), RN7SL126P (81% identical), RN7SL178P (81% identical), RN7SL230P (81% identical), and 705 more.